FGFR4 (fibroblast growth factor receptor 4)
Diseases named in the same sentence as FGFR4 in open-access papers (continued):
Sharing a sentence is not in itself a finding about the gene and the disease.
cancer (continued). "For example, we have previously shown that FGFR4 interaction with the membrane-type matrix metalloproteinase MT1-MMP increases both FGFR4-FRS2-Src kinase signaling and MT1-MMP-driven cancer cell invasion in a Gly388Arg SNP dependent manner." (PMID 33178597, 2020). "Both pan-FGFR and specific FGFR4 inhibitors are in clinical trials for cancer (e.g. NCT02325739; NCT02706691) and would once again be agents worthy of testing in DSRCT patients that express high levels of FGFR4 as part of a combination therapy." (PMID 32703985, 2020). "Highly expressed FGFR4 in the carcinoma tissues is correlated with HCC progression and FGFR4 overexpression has been identified as an oncogenic driver in a subset of patients with HCC." (PMID 32555680, 2020). "There were some RTK genes (EPHB6, EPHA1, EPHB3, FGFR4, PDGFRB, and FLT4) showing amplification in cancer cells." (PMID 32038722, 2019). "Currently, the development and therapeutic evaluation of FGFR4-specific inhibitors, such as BLU9931 and H3B-6527, in animal models and cancer patients, are paving the way to suppress hyperactive FGFR4 signaling in cancer." (PMID 30634399, 2019). "Thus, FGFR4 might play a different role from other FGFRs in malignant tumors." (PMID 28056982, 2017). "The present study revealed the protective role of FGFR4 rs351855 AA genotype against developing an advanced clinical stage (stage III/IV); OR: 0.648; 95% CI: 0.443–0.947) cancer." (PMID 29221201, 2017). "When compared with normal tissues, the expression of FGFR1, FGFR2, and FGFR4 were higher and the expression of FGFR3 was lower in cancer tissues." (PMID 27154171, 2016). "Therefore, the FGFR4 Gly388 allele, but not the Arg388 allele, could exert an effect on the aggressive behaviors of the cancer cells in bladder." (PMID 17088904, 2006). "It is well known that FGFR4 activates the mitogen-activated protein kinase and SRC homology 2 domain-containing phosphatase 2 signaling pathways, thereby maintaining the malignant phenotype in cancer cells." (PMID 41213916, 2025). "Extensive research has been conducted on the role of METTL16 in regulating cancer progression through m6A modification of target genes, including U6 snRNA, MALAT1, XIST, and RAB11B‐AS1, and mRNA (MAT2A, VPS33B, FGFR4, and GPX4)." (PMID 40095756, 2025). "FGFR4 is an exciting therapeutic target because many pan-FGFR inhibitors and FGFR4 inhibitors have been developed, three of which are currently FDA approved for cancer treatment." (PMID 39576839, 2024). "In addition to the receptors FGFR1, FGFR4 and ERBB4, the main effector AKT1 and its downstream effectors, MTOR, GSK3B, p21, WEE1, BAD and CREB5, which mediate cancer cell growth and progression, also exhibited marked changes in HPV-ind CCs." (PMID 38253702, 2024). "FGFR4 binds to FGF19, an important factor in the development and progression of several cancers." (PMID 38540215, 2024). "A recent pan-cancer next-generation sequencing profiling demonstrated that ~7% of cancers harbor gain-of-function FGFR aberrations, with varying frequencies between family members (FGFR1 > FGFR3 > FGFR2 > FGFR4)." (PMID 36839989, 2023). "Both ERBB2 and FGFR4 have been shown to activate ERK and/or Akt in some contexts such as cancer." (PMID 35921893, 2022). "FGFR4 and its ligand (FGF19) are overexpressed in various cancers, including CRCs." (PMID 35194944, 2022). "There have also been many studies that failed to observe any significant contribution of the FGFR4 Gly388Arg SNP to the clinicopathological parameters or prognosis in patients with cancer." (PMID 34737965, 2021). "Since FGF19/FGFR4 signaling acts as an oncogenic pathway and is involved in the cancer progression, targeting FGF19/FGFR4 signaling might be an effective anticancer therapy." (PMID 34576070, 2021). "The patients with high FGFR4 expression also had low survival rates, although the FGFR4 expression level was not significantly different between normal and cancer tissues." (PMID 34639155, 2021).
cancer (continued). "Converging observations indicate that dysregulation of FGFR4 downstream signaling pathways, such as Wnt/β-catenin, JAK/STAT, and PI3K-AKT, leads to enhanced cell growth and metastatic potential in cancer progression." (PMID 34071523, 2021). "These suggest that melatonin may have synergistic anti-cancer functions with FGF19 and FGFR4 inhibitors." (PMID 34576070, 2021). "Concerning additional cancer genes identified in the significantly altered regions, some were characterized as known drivers (SETD2, BAP1, FLT4 and PTEN) and others as predicted drivers (FGFR4 and NSD1), according to the CGI." (PMID 33668731, 2021). "As targeting FGFR4 becomes increasingly more feasible than directly targeting FGF19, highly selective FGFR4 inhibitors have become commercially available for preclinical tests, providing new approaches to treat a subgroup of FGF19-driven cancers." (PMID 33691750, 2021). "To date, the possible involvement of FGF19/FGFR4 signaling in cancer stem cells (CSCs) has not been definitively established." (PMID 33066597, 2020). "First, incubation of RMS cells with FGFR4-sdAb revealed that FGFR4-sdAb can block FGF19-FGFR4 signaling via the MAPK pathway and could therefore serve as therapeutics for FGFR4-dependent cancers." (PMID 33182650, 2020). "More research is needed to fully characterize whether FGFR4 is expressed on subsets of GBM cells, and whether it is functional in these cancers." (PMID 31337028, 2019). "The secretion of FGF family members by CAFs has been shown in multiple different cancer settings: ovarian CAFs secrete FGF-1, leading to phosphorylation of the receptor, FGFR4; breast CAFs secrete FGF-2 and signal via both FGFR1 and FGFR2; and colon CAFs secrete FGF-1 and -3, and signal via FGFR4." (PMID 31861782, 2019). "The electrochemical platform was successfully applied for the determination of FGFR4 in different cancer cell lysates without any apparent matrix effect after a simple sample dilution and using only 2.5 μg of the raw lysate." (PMID 28376106, 2017). "Although altered expression has been documented in breast, lung, pancreatic and prostate cancers, the specific role for FGFR4 in these cancers is not well established." (PMID 27192118, 2016). "A specific role for FGFR4 in cancer is not well established, but altered expression has been documented in breast, lung, pancreatic and prostate cancers." (PMID 17519899, 2007). "Functional and mechanistic analyses revealed that silencing FGF17 suppressed the FGFR4/MEK5/ERK5 signaling cascade, disturbed NRF2-dependent redox homeostasis, and consequently impaired epithelial–mesenchymal transition (EMT), leading to a marked reduction in cancer cell motility and invasiveness." (PMID 41551579, 2025). "Thus, there is no doubt that FGFR4-targeting inhibitors offer the most immediate prospects of reducing cancer mortality rate." (PMID 30634399, 2019). "Unlike FGFR1, the translocation of FGFR4 is very rare in human cancers." (PMID 30634399, 2019). "No data for FGFR4 protein levels have been reported for the other cancer cells tested in our assay." (PMID 28376106, 2017). "No such effect was observed in the FGFR4−/FGF19+ MDA-MB-231 cells or in the FGFR−/FGF19− MCF-10A cells, suggesting that only cancer cells that co-expressed FGFR4 and FGF19 might be susceptible to FGFR4/FGF19 inhibition." (PMID 27192118, 2016). "In addition to the recurrent and early 11p LOH event in fusion negative tumors, mutation of FGFR4, KRAS, NRAS and HRAS frequently occurred at an early time point in the cancers evolutionary history." (PMID 25768946, 2015). "FGF8, FGF18, and FGFR4 have been identified as promising biomarkers in a number of cancers; however no data exist on expression of FGF8, FGF18, and FGFR4 in adenocarcinomas of the esophago-gastric junction (AEG)." (PMID 31527546, 2019).
cancer (continued). "Intriguingly, depletion of endogenous FGFR4 has no such effect on the luminal-like MCF-7 and HER2-amplified SKBR3 cells, suggesting that FGFR4 mediates cancer cell survival in a cell context-dependent manner." (PMID 27192118, 2016). "For instance, FGFR4 (fibroblast growth factor receptor 4) was noted to be highly expressed only in RMS and not in normal muscle, but it is also expressed in some other cancers and normal tissues." (PMID 15784140, 2005). "In more detail, it explains heterogeneity in FGFR4 expression both across PAM50 subtypes and in cancer cell lines, but also within HER2E tumors irrespective of ERBB2 status, and may even be potentially informative as a biomarker for FGFR4 inhibitors." (PMID 40044693, 2025). "However, lenvatinib alone could inhibit HCC cancer stem-like cells through FGFR1-3 signaling, but not FGFR4 signaling." (PMID 34884875, 2021).
infection (5 papers, 2013 to 2025). The state of being infected such as from the introduction of a foreign agent such as serum, vaccine, antigenic substance or organism. "Given the differences seen in phospho-PLCγ due to PA infection alone compared to the uninfected control, we inhibited FGFR4 using BLU9931—an FGFR4 isoform specific inhibitor—at 0.1 μM prior to PA infection for 1 h." (PMID 37763754, 2023). "Infection triggered significant reductions in the intestinal expression of Fgf15 and its hepatic receptor components (Fgfr4 and Klb (βKlotho))." (PMID 24165751, 2013). "Fibroblast growth factor (FGF)-23, TFRC, FGFR4, and ATPase H+ transporting V0 subunit B (ATP6V0B) were the upregulated genes identified in A. baumannii without resistant gene infection-associated pulmonary host responses." (PMID 39857726, 2025). "Validation of the gene expression levels obtained by RNA-seq specific to the HCV group (BIRC5 and SLC22A1), the HBV group (CLEC1B), and the group without infection (FGFR4, HSF1, RNF187, HSP90AB1, and HSPB1) was performed using the real-time PCR technique." (PMID 36557005, 2022). "Additionally, PA infection affects the mRNA levels of certain subtype-specific FGFRs—namely, FGFR1, 2 and 3, but not FGFR4—although FGFR inhibition did not affect PA-mediated inflammation." (PMID 37763754, 2023).
metabolic disorders (5 papers, 2013 to 2023). "In this study, tylosin TMDI-treated mice showed increased PBA/SBA ratios and lower FGF15 levels in the ileum and portal vein, thereby decreasing the expression of hepatic FGFR4, which may cause metabolic disorders by affecting metabolism-related signaling pathways in the liver (46, –, 48)." (PMID 35670534, 2022). "Collectively, tylosin TMDI-treated mice showed an increased PBA/SBA ratio, as well as lower FGF15 levels in the ileum and portal vein, and decreased expression of hepatic FGFR4, which may cause metabolic disorders by affecting metabolism-related signaling pathways in the liver (46, –, 48)." (PMID 35670534, 2022). "Hepatic silencing of FGFR4 leading to activation of the intestinal FXR-FGF15/19 axis could be a promising strategy to treat metabolic disorders induced by HFD." (PMID 36586437, 2023).
adenocarcinoma (4 papers, 2007 to 2019). A common cancer characterized by the presence of malignant glandular cells. "Until now, no data exists on the expression of FGF8, FGF18, and FGFR4 on adenocarcinomas of the esophago-gastric junction investigated by immunohistochemistry and no signifier scoring method is available." (PMID 31527546, 2019).
bacterial infection (3 papers, 2013 to 2025). "Collectively, these data define a multi‐tiered signaling cascade where bacterial infection activates Wnt to induce gcFGF8a, which binds to FGFR4 to drive ERK/AKT‐mTORC1‐HIF1α signaling, thereby creating a pro‐repair environment." (PMID 40586300, 2025). "Our study elucidated a novel signaling axis linking bacterial infection, Wnt‐dependent gcFGF8a induction, and FGFR4‐mediated mTORC1‐HIF1α activation in teleost wound repair." (PMID 40586300, 2025). "In this work, we examined the disruption of the enterohepatic fibroblast growth factor 15/19 (FGF15/19)-fibroblast growth factor receptor 4 (FGFR4) endocrine axis during bacterial infections of the enterohepatic system." (PMID 24165751, 2013). "Viral and bacterial infection increases mRNA levels of Sp-FGFR3 in the hepatopancreas and Pc-FGFR4 in hemocytes and hepatopancreas." (PMID 38638139, 2024). "The biology of FGFR4 and βKlotho had never before been studied in the context of a bacterial insult, and our data suggest that their function can be severely compromised by bacterial infections in vivo." (PMID 24165751, 2013).
kidney disease (2 papers, 2018 to 2019). "Differences between Hyp and kl/kl mice regarding characteristics of cardiovascular and kidney disease, cardiac FGF23/FGFR4 system, and parameters of mineral metabolism." (PMID 29977226, 2018). "FGF23 has also been shown to independently predict progression of renal disease, however, whether FGF23 and FGFR4 also contribute to CKD remains unknown." (PMID 31575945, 2019).
cardiovascular disease (1 paper, 2019). "Taken together our results suggest FGFR4 inhibition as a safe alternative strategy to target cardiovascular disease and chronic inflammation in patients with CKD without interrupting the necessary phosphaturic effects of FGF23." (PMID 31575945, 2019).
head and neck tumor (1 paper, 2021). "However, we at least provide a principle of concept that the determination of serum MT levels may enable to predict the levels of FGF19 in head and neck tumor tissues, which would be beneficial for FGFR4-based therapeutics." (PMID 33691750, 2021).
inflammation (1 paper, 2022). Aberrant reaction of the microcirculation characterized by movement of fluid and leukocytes from the blood into extravascular tissues. "The expression of FXR and FGFR4 are also downregulated during NASH development, and FXR activation is protective against liver inflammation associated with NASH." (PMID 35163821, 2022).
intestinal disorder (1 paper, 2024). A non-neoplastic or neoplastic disorder that affects the small or large intestine. "BAD is a prevalent intestinal disease characterized by the multifaceted involvement of FXR, FGFR4, and TGR5 in its pathogenesis." (PMID 38338820, 2024). "Bile acid diarrhea (BAD) is a multifaceted intestinal disorder involving intricate molecular mechanisms, including farnesoid X receptor (FXR), fibroblast growth factor receptor 4 (FGFR4), and Takeda G protein–coupled receptor 5 (TGR5)." (PMID 38338820, 2024).
FGFR4 also shares sentences with these, for which no sentence is quoted: lung squamous cell carcinoma (4 papers); metabolic syndrome (4); Glucose intolerance (3); hyperlipidemia (3); neuroblastoma (3); alveolar rhabdomyosarcoma (2); anemia (2); colon adenocarcinoma (2); cystic fibrosis (2); Hyperglycemia (2); hypertrophy (2); infectious disease (2); multiple myeloma (2); Myocardial fibrosis (2); ovarian tumor (2); pheochromocytoma (2); pituitary adenocarcinoma (2); renal cell carcinoma (2); respiratory distress syndrome (2); sarcopenia (2); type 2 diabetes (2); Abdominal obesity (1); adenocarcinomas of the breast (1); adenosquamous carcinoma (1); alcohol (1); basal cell carcinoma (1); bile duct cancer (1); bladder tumor (1); bladder urothelial cancer (1); bronchioloalveolar carcinoma (1).
A further 68 diseases each share a sentence with FGFR4 in 1 paper.